CHM (CHM Rab escort protein)
Diseases named in the same sentence as CHM in open-access papers (continued):
Sharing a sentence is not in itself a finding about the gene and the disease.
choroideremia (continued). "For Choroideremia (CHM), an X-linked retinal disorder which results from defects in the human Rab escort protein-1 (REP-1) gene, disruption of the mouse rep-1 gene gives rise to lethality in male mouse embryos." (PMID 36658594, 2023). "Physiological interactors of Rab 7 are RILP, OSBP and the Rab escort protein 1 or CHM choroideremia protein, which is the substrate-binding subunit of the Rab geranylgeranyltransferase complex." (PMID 37243184, 2023). "Choroideremia is caused by mutations in the CHM gene, which encodes Rab escort protein 1 (REP1), a ubiquitously expressed 653-amino acid protein that forms an essential component of the catalytic Rab geranyl-geranyl transferase (RGGTase) II complex." (PMID 37894906, 2023). "Choroideremia is an X-linked recessive disorder characterized by a frameshift mutation in the CHM gene, which encodes Rab escort protein 1 (REP-1) and is important for intracellular protein trafficking." (PMID 36293232, 2022). "Clinical review of this patient indicated a likely diagnosis of choroideremia, however, molecular testing of CHM/REP1 precluded this diagnosis." (PMID 33776059, 2021). "Here, we report molecular characterization of seven large deletions that remove in part or all the CHM gene in Italian patients with choroideremia." (PMID 34440285, 2021). "For IRDs, promising results using PTC124 have been reported by the restoration of full-length RP2 protein, the encoding gene of which is mutated in X-linked RP, as well as for the REP1 protein, encoded by the CHM gene that is mutated in choroideremia." (PMID 31466352, 2019). "In this regard, choroideremia is different to retinitis pigmentosa, because the unique choroideremia phenotype can justify the additional resources needed to sequence the entire CHM genomic region." (PMID 31548516, 2019). "REP family consists of only 2 members: choroideremia (CHM, REP1) and choroideremia-like (CHML, REP2)." (PMID 31175290, 2019). "The CHM gene caused only choroideremia, an X-linked form of IRD, and about 60% of patients with a mutation in the CHM gene had large deletions ranging from loss of two exons to deletion of the entire coding region." (PMID 30374144, 2018). "To conclude, this is the first report of molecular analysis of the CHM gene in Polish patients suffering from choroideremia." (PMID 30541579, 2018). "Mutations in Rab escort protein-1 (REP-1 or CHM), which facilitates geranylgeranyl transfer onto unprenylated Rab GTPases, cause choroideremia — an X-linked retinal degeneration characterized by profound loss of the outer retina and choriocapillaris." (PMID 29321376, 2018). "As an aspect of pathophysiology, mutations in REP1 cause a disease called choroideremia (CHM), which is known as an X-linked eye disease resulting from progressive degeneration of multiple tissues including photoreceptors, retinal pigment epithelium, and choriocapillaris." (PMID 28846638, 2017). "Somatic mosaicism has been described for disease-causing insertions as in a LINE-1 retrotransposition event into the choroideremia (rab escort protein 1) (CHM) gene." (PMID 27158268, 2016). "Choroideremia is an X-linked recessive defect in the CHM protein, which encodes the rab escort protein (REP1)." (PMID 27847630, 2016). "Choroideremia is an inherited disorder due to loss of the CHM gene and the resulting Rab Escort Protein 1 (REP-1), which leading to degeneration of the choroid and retina and blindness by the 2nd decade of life." (PMID 26239347, 2015). "One such disease, choroideremia (CHM), is an X-linked chorioretinal degeneration caused by functional defects in CHM/REP1, a chaperone protein for Rab GTPases, which are critical regulators of membrane trafficking." (PMID 23460904, 2013). "The choroideremia gene, CHM, encodes Rab Escort Protein-1 (REP-1), a 653 amino acid protein thought to be involved in membrane trafficking." (PMID 23667438, 2013).
choroideremia (continued). "CHM gene molecular analysis and X-chromosome inactivation pattern determination in two families with choroideremia." (PMID 22025891, 2011). "Choroideremia (CHM) is a progressive X-linked retinopathy caused by mutations in the CHM gene, which encodes Rab escort protein-1 (REP-1), an escort protein involved in the prenylation of Rabs." (PMID 20027300, 2009). "LYST (lysosomal trafficking regulator, also known as CHS1) is the causal gene for Chediak-Higashi syndrome, an inherited immunodeficiency disease, and CHM (Rab escort protein 1) is responsible for an inherited human retinal blindness known as choroideremia." (PMID 17915034, 2007). "Notably, we identified an intragenic inversion in CHM that segregated with the choroideremia phenotype." (PMID 40571344, 2025). "Choroideremia is a rare X-linked recessive retinal disorder characterized by progressive vision loss caused by retinal degeneration resulting from mutations in the CHM gene, which encodes Rab escort protein 1 (REP-1)." (PMID 40332248, 2025). "It has been hypothesized that relatively low expression of the homologous CHML gene in RPE cells could contribute to the eye-specific phenotype of choroideremia despite ubiquitous expression of CHM." (PMID 38920696, 2024). "Choroideremia, a monogenic X‐linked chorioretinal dystrophy, manifests as a progressive degeneration of RPE, choroid, and retina caused by mutations in the CHM gene, which encodes Rab escort protein 1 (RPE1), a ubiquitously expressed protein critical for Rab protein prenylation." (PMID 39156766, 2024). "Examples include achromatopsia (AAV-CNGA3; NCT03758404 and NCT03001310), X-linked RP (XLRP) [AAV8-RP guanosine triphosphatase regulator (RPGR); NCT03116113], choroideremia (CHM) [AAV2-Rab escort protein-1 (REP1); NCT03507686], and neovascular AMD (rAAV-sFlt-1; NCT01494805)." (PMID 38188726, 2023). "However, since the CHM gene is only 1.9 kb, there have been studies showing progress in treating choroideremia using AAV gene therapy to enhance the transgene expression." (PMID 36293232, 2022). "Thus, it is worth postulating a hypothetical model in which the biallelic expression of CHM would concur in the manifestations of Choroideremia in females." (PMID 35886051, 2022). "In humans two REP homologues have been identified and while the consequences of REP‐2 (CHML) deficiency are not known, the deficiency of REP‐1 (CHM) leads to progressive retinal dystrophy – choroideremia." (PMID 34592024, 2021). "We suggest that cases of choroideremia with negative CHM sequencing should be tested for this RPE65 variant." (PMID 33776059, 2021). "Therefore, as also the CHM gene - involved in choroideremia onset - was deleted, we carried out a detailed ophthalmological study on individuals III-1 and III-2." (PMID 25821518, 2015). "Specifically, we detected pathogenic DNA variants (∼50% novel mutations) in the genes RP1, USH2A, CNGB3, NMNAT1, CHM, and ABCA4, responsible for retinitis pigmentosa, Usher syndrome, achromatopsia, Leber congenital amaurosis, choroideremia, or recessive Stargardt/cone-rod dystrophy cases." (PMID 23940504, 2013). "Since the CHM locus is on the X-chromosome, choroideremia is typically only diagnosed in males." (PMID 23667438, 2013). "Choroideremia (CHM) has been recognized as clinically distinct from other retinal degenerations for more than half a century, and is known to be a genetic heterogeneous X-linked recessive disease associated with different types of mutations in the CHM gene (CHM)." (PMID 22025891, 2011). "Mutations in the CHM gene, resulting in a loss of function for its product protein, Rab escort protein-1 (REP-1), has been linked to causing choroideremia (CHM)." (PMID 36830640, 2023). "X-linked choroideremia (CHM) is characterized by gradual degeneration of the RPE, photoreceptors and choriocapillaris and is caused by loss of function of Rab Escort Protein-1 (REP1)." (PMID 33201897, 2020).
choroideremia (continued). "Advanced methods such as WGS (Whole Genome Sequencing) may be required in some unsolved cases of choroideremia, as deep intronic mutations in the CHM gene, which failed to be detected with conventional techniques, cannot be excluded." (PMID 30541579, 2018). "MIR361 is encoded on the × chromosome, in an intron between exons 9 and 10 of CHM/choroideremia (Rab escort protein 1) and gives rise to two mature miRNA species, miRNA-361-3p and the predominant miRNA-361-5p." (PMID 23166713, 2012). "Choroideremia (CHM) is an X-linked inherited chorioretinal dystrophy caused by mutation or deletion of the CHM gene, leading to the absence of Rab-escort protein 1 (REP-1)." (PMID 38594294, 2024). "The same experimental approach was then performed using CHM cDNA—the gene responsible for choroideremia, formerly known as REP1 (Rab escort protein 1)—as representative of a clinical scenario." (PMID 28325286, 2017). "As deafness and choroideremia are commonly observed in all the recorded cases, POU3F4 and CHM gene deletions are two basic indexes for diagnosis." (PMID 28630650, 2017). "A recent gene therapy trial using subretinal delivery of AAV-packaged CHM for gene augmentation in choroideremia failed to meet its primary endpoint, which was an improvement in the visual acuity of 15 letters (NCT03496012)." (PMID 38920696, 2024). "Torin increased autophagic flux in CHM−/− iPSC-RPE more than control iPSC-RPE cells (3.6-fold vs. 1.2-fold, p < 0.0001), thus supporting the role of mTOR signaling in reducing autophagic flux in choroideremia." (PMID 38920696, 2024). "Furthermore, partial knockdown of Rab12 in control iPSC-RPE cells reproduced the increased mTORC1 signaling and reduced the autophagy phenotype seen with CHM knockout, further supporting the importance of Rab12 in RPE autophagic dysfunction in choroideremia." (PMID 38920696, 2024). "Sanger sequencing of the CHM coding sequence, alternatively MLPA assay in combination with non-invasive fundus imaging performed and analyzed by experienced ophthalmologists, is usually sufficient to make a diagnosis of choroideremia." (PMID 30541579, 2018). "It has been shown that a contiguous gene Xq21 deletion, including POU3F4, CHM and ZNF711 genes, could result in choroideremia, deafness, and mental retardation syndrome." (PMID 28630650, 2017). "Phenotype variations within a choroideremia family lacking the entire CHM gene." (PMID 22025891, 2011).
retinitis pigmentosa (6 papers, 2013 to 2025). Retinitis pigmentosa (RP) is an inherited retinal dystrophy leading to progressive loss of the photoreceptors and retinal pigment epithelium and resulting in blindness usually after several decades. "We described a family with an initial clinical suspicion of Retinitis Pigmentosa in which a novel CHM pathogenic splicing variant was found by exome sequencing." (PMID 35886051, 2022).
retinal disease (4 papers, 2004 to 2025). "This is illustrated by the finding that the 15K retinome which comprises 15,645 transcripts including those which were solely found in a single study, contains an additional five of the 102 known retinal disease genes (RHOK, MTATP6, CHM, LRAT, RIMS1) not included in the 13K retinome." (PMID 15283859, 2004).
retinal dystrophies (4 papers, 2018 to 2026). "Lately, there have been reports of some patients with mutations in the CHM gene identified using NGS (Next Generation Sequencing) panel for inherited retinal dystrophies or even WES (Whole Exome Sequencing) as a molecular method of choice." (PMID 30541579, 2018). "To date, proof‐of‐concept of AONs has been shown in both cell‐based models and animal models for four retinal dystrophy genes: CEP290, CHM (Garanto, van der Velde‐Visser, Cremers, & Collin, 2018), RHO, and USH2A, and represents a promising therapy for retinal dystrophies." (PMID 30950243, 2019). "CHM is unlikely to be an isolated retinal dystrophy due to the ubiquitous expression of REP1." (PMID 33755601, 2021).
depression (3 papers, 2017 to 2022). "A major contribution of this study is the identification of specific CHM products associated with the observed lower risk of depression in breast cancer patients." (PMID 36059752, 2022).
Atrophy (2 papers, 2025). Any weakening or degeneration, especially through lack of use. "In contrast, CHM carriers are typically classified as having intermediate disease characterised by the presence of atrophy, irrespective of its geographic location." (PMID 40004550, 2025).
breast carcinoma (2 papers, 2016 to 2022). "The top two hits were from studies on diffuse large B cell lymphoma (GEO accession GSE10846) and breast cancer (GEO accession GSE24450), and both showed that poor survival was significantly associated with low expression of CHM (respectively)." (PMID 27685995, 2016).
Chorioretinal atrophy (2 papers, 2017 to 2020). Atrophy (wasting) of the choroid and retinal layers of the fundus. "A mutation in CHM, which expresses REP-1, leads to chorioretinal degeneration starting in the mid-periphery." (PMID 28134823, 2017). "Variants in the CHM gene can lead to a deficiency of REP-1 and the onset of chorioretinal atrophy." (PMID 32364220, 2020).
Hearing impairment (2 papers, 2017 to 2021). A decreased magnitude of the sensory perception of sound. "The deleted region harbors 12 OMIM genes, of which POU3F4, CHM, and ZNF711 might have contributed to the patient’s phenotype including hearing loss, poor vision, and intellectual disability." (PMID 28630650, 2017). "Interestingly, a large deletion involving CHM and the neighboring POU3F4 and ZNF711 genes has been previously identified in a CHM patient with hearing impairment and developmental disability." (PMID 34440285, 2021).
Macular dystrophy (2 papers, 2021 to 2022). Macular dystrophy is a nonspecific term for retinal degeneration, generally confined to the macula, usually presumed of genetic origin. "Heterozygous individuals in ABCA4 disease and control cohort harboring rare variants in macular dystrophy genes CDHR1, CHM, CRX, ELOVL4, PROM1, PRPH2, ROM1." (PMID 35353811, 2022). "Heterozygous individuals in ABCA4 disease and control cohort harboring variants with MAF<0.005 and CADD score >25, in each macular dystrophy gene CDHR1, CHM, CRX, ELOVL4, PROM1, PRPH2, and ROM1." (PMID 35353811, 2022).
gallstones (1 paper, 2022). Solid crystalline precipitates in the biliary tract, usually formed in the gallbladder, resulting in the condition of cholelithiasis. "Moreover, hepatic cholesterol content was lower in litho+hypo compared to litho only and control conditions in female but not male mice which could contribute to ChM crystal and cholesterol gallstone formation in the bile of female mice under litho+hypo condition." (PMID 36293210, 2022).
osteosarcoma (1 paper, 2016). A usually aggressive malignant bone-forming mesenchymal neoplasm, predominantly affecting adolescents and young adults. "However, we found the expression level to be significantly downregulated in both OS cell lines and clinical samples compared to the control samples, which supports the assumption of an inhibitory role for CHM in osteosarcoma biology." (PMID 27685995, 2016).
cancer (7 papers, 2016 to 2025). A tumor composed of atypical neoplastic, often pleomorphic cells that invade other tissues. "Using DRUGSURV, a publicly available database where expression profiling and clinical information from several studies are available, we investigated the expression of CHM in other cancer types." (PMID 27685995, 2016). "We propose, to our knowledge, for the first time a role for CHM in cancer biology, although more thorough studies are necessary to investigate the potential tumor suppressive function of REP-1." (PMID 27685995, 2016). "Together, these data suggest CHM as a candidate tumor suppressor gene in cancer, but the potential mechanism has to be further elucidated." (PMID 27685995, 2016). "Therefore, SCAMP1 and CHM may play a role in regulating the growth, survival and invasion of cancer cells." (PMID 40458711, 2025). "In this study, we first demonstrate that REP1 expression is upregulated in cancer cells and cancer patient tissue and that REP1 (CHM) functions as an oncogene." (PMID 28230863, 2017).
infection (6 papers, 2013 to 2022). The state of being infected such as from the introduction of a foreign agent such as serum, vaccine, antigenic substance or organism. "In fact, transgene expression of wild type CHM copies through adeno-associated virus (AAV) vectors’ infection of retinal cells would not suffice in restoring physiological prenylation of Rab proteins due to competition between the mutated and the wild type transfected CHM alleles for RGGT binding." (PMID 35886051, 2022).
tumor (3 papers, 2016 to 2017). "Although still not strongly supported in OS, we propose CHM (choroideremia (Rab escort protein 1)) to be a candidate tumor suppressor gene." (PMID 27685995, 2016). "Together, these results suggest CHM as a candidate tumor suppressor gene that warrants further investigation." (PMID 27685995, 2016).
autosomal recessive disease (1 paper, 2018). Autosomal recessive form of disease. "Other more representative genes were CEP290, USH2A, and CRB1 that caused autosomal recessive diseases and RPGR and CHM that caused X-linked IRD; each one accounted for about 5% of the conclusive results." (PMID 30374144, 2018).
neurodevelopmental disorder (1 paper, 2024). A behavioral and cognitive disorder with onset during the developmental period that involves impaired or aberrant development of intellectual, motor, or social functions. "Also, we have identified 15 de novo variants in genes that were previously implicated in ASD or related neurodevelopmental disorders (PHF21A, WASF1, TCF20, DEAF1, MED13, CREBBP, KDM6B,SMURF1, ADNP, CACNA1G, MYT1L, KIF13B, GRIA2, CHM, and KCNK9)." (PMID 38572415, 2024).
CHM also shares sentences with these, for which no sentence is quoted: retinal degeneration (13 papers); Parkinson disease (5); achromatopsia (4); colorectal cancer (4); Blindness (3); Cognitive impairment (2); colon cancer (2); deafness (2); dementia (2); hemangioma (2); Intellectual disability (2); Leber congenital amaurosis (2); Leber hereditary optic neuropathy (2); retinoschisis (2); Usher syndrome (2); Visual hallucination (2); X-linked disease (2); X-linked recessive disease (2); adenocarcinoma (1); adenovirus infection (1); Alzheimer disease (1); Anhidrotic ectodermal dysplasia (1); asthma (1); Astigmatism (1); autism (1); Chediak-Higashi syndrome (1); choroidal (1); choroidal degeneration (1); cognitive decline (1); cognitive disease (1).
A further 28 diseases each share a sentence with CHM in 1 paper.